TNF (tumor necrosis factor)
Diseases named in the same sentence as TNF in open-access papers (continued):
Sharing a sentence is not in itself a finding about the gene and the disease.
periodontitis (continued). "Catechin administered at 200 mg/kg in ligature induced rat periodontitis model, reduced alveolar bone loss, down regulated IL-6, and TNF-alpha expression indicating its therapeutic effect on damaged periodontal tissue." (PMID 30925801, 2019). "Recent research demonstrated that alteration in methylation levels of IL 6, TNF α and IL 8 gene promoters have been reported in association with periodontitis in either gingival tissues or oral epithelial cells." (PMID 31554202, 2019). "T-cells from patients with inflammatory bone loss diseases secrete more TNF-α, as shown for psoriatic arthritis, osteoporosis, periodontitis, and Turner's syndrome." (PMID 30941138, 2019). "Mast cell-derived TNF-α has also been reported to promote bone loss in periodontitis induced by oral cavity infection with Porphyromonas gingivalis." (PMID 31416928, 2019). "Another cross-sectional study demonstrated that the increased serum levels of TNF-α and IL-6 in patients with AD were significantly associated with periodontitis." (PMID 31366073, 2019). "TNF-α is a sensitive marker of alveolar bone loss observed in periodontitis and peri-implantitis cases." (PMID 31596364, 2019). "The increase in systemic markers of inflammation such as C-reactive protein, interleukin 6, and tumor necrosis factor-α in the plasma of periodontitis patients supports this association." (PMID 31195790, 2019). "Current research has shown that supplementation with different forms of 1,25D3 regulates the expression of inflammatory cytokines, such as TNF-α and IL-8, in oral epithelial cells, and reduces alveolar bone loss in periodontitis." (PMID 31684930, 2019). "Periodontitis is reported as one of the main factors that cause tooth loss and is linked to an augmentation of interleukin-1 (IL-1), tumor necrosis factor-α (TNF-α), and IL-6, which are well-known pro-inflammatory agents." (PMID 31052367, 2019). "Statins were shown to suppress inflammatory factors associated with periodontitis such as IL-6, TNF-α, IL-1β, as well as periodontal pathogens Pg and Aa." (PMID 31196047, 2019). "The main cause of periodontitis, bacterial plaque, triggers production of key cytokines, such as IL-1β and TNF-α, from macrophages." (PMID 31027223, 2019). "In the Indian population, especially the eastern Indian people with periodontitis, to the best of our knowledge, the present study is the first to evaluate polymorphisms of TNF-α." (PMID 29449347, 2018). "This is indicative of the key association between chronic periodontitis and higher levels of visfatin, IL-6, and TNF-α." (PMID 30186882, 2018). "Tumor necrosis factor plays a central role in periodontitis, being associated with the disease because of its ability to induce destruction of connective tissue and its effects on bone resorption through the activation of osteoclasts." (PMID 30467497, 2018). "TNF-α gene polymorphisms at the promoter region have been intensively studied and some of them were shown to be associated with the severity of periodontitis." (PMID 29449347, 2018). "We investigated the association of single nucleotide polymorphisms (SNPs) in TNF-α gene promoter region with the susceptibility of aggressive and chronic periodontitis in the eastern Indian population." (PMID 29449347, 2018). "It is imaginable that individual differences in periodontitis susceptibility or individual differences in periodontal disease severity are related to genetically determined differences in TNF-α production and secretion by a variety of cells." (PMID 29449347, 2018). "Some studies have been conducted to evaluate the association between TNF-α promoter polymorphisms and periodontitis in different populations, but it is still a contradictory topic of debate." (PMID 29449347, 2018). "The present study sought to investigate the effect of TNF-α (-238G/A, -308 G/A, -857C/T, -863C/A, and -1031 T/C) gene promoter SNPs on susceptibility to periodontitis in the Indian population." (PMID 29449347, 2018).
periodontitis (continued). "Nevertheless, a recent study with a bigger sample of preconception women with periodontitis showed a positive association between elevated concentrations of IL-1β, β-glucuronidase, and TNF-α in saliva and serum." (PMID 29017560, 2017). "This suggests that TNF-α is associated with alveolar bone loss in type 1 diabetes with periodontitis." (PMID 29240821, 2017). "Studies have shown that other salivary inflammatory markers, including tumor necrosis factor- alpha, matrix metaloproteinases, interleukin-6, and interleukin-8, are associated with dental health and periodontitis." (PMID 28253297, 2017). "Many researchers have attempted to find useful biomarkers such as TNF-α, IL-10, IL-17, IL-12, and IL-1β in saliva that are associated with periodontitis to help predict or diagnose T2DM." (PMID 29109737, 2017). "In previous studies, type 1 diabetes rats with periodontitis have shown higher TNF-α expression and alveolar bone loss than rats with periodontitis." (PMID 29240821, 2017). "TNF-α, an inflammatory cytokine, is strongly implicated in the induction of tissue destructive responses occurring during periodontitis." (PMID 28264048, 2017). "It is concluded by the authors that impaired TNF-α–p55TNF-R1 signaling causes protection against periodontitis through dampening of PMN invasion, hereby likely attenuating the osteoclastogenic response, despite a higher bacterial pressure." (PMID 29163477, 2017). "RA and periodontitis exhibit similar pathological features that are associated with the overproduction of pro-inflammatory cytokines such as interleukin-6 (IL-6) and tumor necrosis factor-alpha (TNF-α)." (PMID 27111223, 2016). "It has been well recognized that both periodontitis and RA are associated with persistent high levels of pro-inflammatory cytokines including TNF-α, IL-1, and IL-6." (PMID 25657893, 2015). "A number of animal studies have indicated a significant role for TNF-α in the alveolar bone loss that is a main characteristic of periodontitis." (PMID 25657893, 2015). "Both RA and periodontitis are associated with bone destruction, mediated by inflammatory cytokines such as interleukin 1 (IL-1), tumor necrosis factor-alpha (TNF-α), and prostaglandin E2." (PMID 25506439, 2014). "TNF-α is a potent pleiotropic proinflammatory cytokine and has been implicated in the pathogenesis of periodontitis." (PMID 25179218, 2014). "Genes known to be associated with peri-implantitis and periodontitis were tested for their presence in our case group; IL-1A, IL-1B, and TNF all appeared in our dataset." (PMID 24921256, 2014). "A strong association between Tumor Necrosis Factor Alpha (TNF-α) rs1800629 and generalized forms of periodontitis was found." (PMID 24274085, 2013). "Our findings also show that the GG genotype of TNF-α is a genetic risk factor for periodontitis (OR = 2.463)." (PMID 24274085, 2013). "A TNF-α promoter SNP (-308) has also been associated with the development of the disease and aggressive periodontitis." (PMID 24274085, 2013). "The C allele of Vascular Endothelial Growth Factor, A allele of Interleukin 10 and GG genotype of Tumor Necrosis Factor-α were individually associated with chronic periodontitis." (PMID 24274085, 2013). "Periodontitis is associated with a decreased abundance of fibroblasts and TNF-α has been shown to be an important mediator of P. gingivalis-induced apoptosis." (PMID 23841502, 2013). "The concomitant presence of C allele of the VEGF gene, the A allele of the IL-10 gene and the G allele of the TNF-α gene ("triple SNP signature") is highly increased in patients with periodontitis (OR = 7.375)." (PMID 24274085, 2013). "The odds ratio for carriage of TNF-α allele (A/A and A/G genotypes combined to compare with the G/G genotype) was 3.716 (95% CI = 1.943 - 7.104) in periodontitis patients." (PMID 23046796, 2012).
periodontitis (continued). "Its role and its contribution to the pathogenesis of chronic periodontitis, tissue destruction and bone loss has been clearly documented and administration of anti-TNF-α antibodies resulted in reduced alveolar bone loss." (PMID 22457623, 2012). "CRP, IL-1β, IL-6, and TNF-α have been associated with the presence of various bacterial infections including periodontitis." (PMID 22966213, 2012). "The surface of inflammatory infiltrate, alveolar bone loss, attachment loss, and expression of IL-1β and TNF-α in the stress group were higher than those in the periodontitis group at weeks 2 and 4 (P < 0.05)." (PMID 23326020, 2012). "For instance, it has been shown that attachment loss is decreased in periodontitis patients after anti-TNF treatment, and subcutaneous administration of recombinant TNFα is demonstrated to exacerbate experimental periodontitis in rats." (PMID 20398340, 2010). "Given the biological properties associated with TNF-α and IL-8, they are likely to contribute to periodontitis." (PMID 22069588, 2010). "Consequently, nicotine exacerbates susceptibility to periodontitis by inhibiting TNF-α responses, thus diminishing the immunological defence against pathobionts." (PMID 41157245, 2025). "Notably, IL-6 and TNF-α are two key cytokines that significantly contribute to the inflammatory process associated with periodontitis." (PMID 40085302, 2025). "Similarly, low birth weight labor is linked to periodontitis through intermediary pro-inflammatory cytokines and chemokines, namely TNF-α, IL-1β, CRP, IL-1, IL-6 and IL-18." (PMID 41394354, 2025). "In addition, the possible modulating effects of TNF-α, a pro-inflammatory cytokine associated with periodontitis, on PRF-induced effects were studied." (PMID 41153647, 2025). "In vivo, the exclusive reliance on a rat periodontitis model lacks representativeness, and the restricted focus on two inflammation-associated cytokines (TNF-α and IL-1β) overlooks other critical mediators (e.g. IL-6) and bone formation markers (e.g. BMP-2, OCN)." (PMID 40958806, 2025). "The proposed explanation for this association is based on the idea that periodontitis could influence inflammatory biomarkers, such as TNF-α, Interleukin 1 Beta (IL-1β), and Interleukin 6 (IL-6), which may contribute to increased blood pressure." (PMID 40002786, 2025). "Interestingly, TNF-α polymorphisms were linked to the increased risk of periodontitis in some population groups." (PMID 41021535, 2025). "Similar to periodontitis, inflammation in periimplantitis is associated with elevated levels of pro-inflammatory cytokines such as interleukin-1β (IL-1β), interleukin-6 (IL-6), and tumor necrosis factor-alpha (TNF-α)." (PMID 40217900, 2025). "In a rat periodontitis model, cashew gum polysaccharide (CG‐P)‐containing oral gel significantly reduced alveolar bone loss, decreased the mRNA expression of TNF‐α, IL‐1β, RANKL, and the RANKL/OPG ratio, and lowered myeloperoxidase activity in gingival tissues." (PMID 41476843, 2025). "In this study, we found that periodontitis and periodontitis-associated metabolite Ile enhanced NF-κB signaling in IECs to impair epithelial barrier function and increase the expression of pro-inflammatory cytokines (TNF-α, IL-6, and IL-1β)." (PMID 41394102, 2025). "Similarly, “inflammatory depression” induces a functional alteration of the HPA axis with increased secretion of pro-inflammatory cytokines such as IL-6 and TNF-α; the latter are in turn associated with the development of periodontitis." (PMID 39124790, 2024). "The proinflammatory signaling cascade triggered in periodontitis causes hyperpermeability of endothelial cells and the subsequent release of cytokines/interleukins (TNF-α, IL-1, IL-6) into the bloodstream, which affect endothelial function, causing alterations in the vascular structure." (PMID 38396672, 2024).
periodontitis (continued). "Periodontitis is an inflammatory disease, often associated with the presence of P. gingivalis in subgingival biofilms, which destroys tissues by releasing pro-inflammatory cytokines such as IL-1β and TNF-α." (PMID 38921772, 2024). "Deregulation of TNF-α has been implicated in the pathogenesis of periodontitis." (PMID 38323815, 2024). "Additionally, genetic variations in the TNF-α gene are associated with increased susceptibility to periodontitis and more severe disease progression." (PMID 39189252, 2024). "According to existing knowledge, variants of at least 65 genes are associated with the risk of periodontitis and polymorphisms, including genes encoding IL-1 (interleukin 1), tissue compatibility system (HLA) molecules, and TNF-α (tumor necrosis factor alpha), among others." (PMID 38473967, 2024). "Proinflammatory cytokines, such as IL-1, tumor necrosis factor alpha (TNF-α), and IL-6, are implicated in the pathogenesis and progression of the periodontitis and furthermore would seem to allow an increase of the atheromatous lesion inducing the formation of a greater number of spongy cells." (PMID 39034949, 2024). "Moreover, increased serum levels of soluble TNF were observed in patients with periodontitis as compared to healthy controls and were associated with dental plaque load (Aggregatibacter actinomycetemcomitans and Porphyromonas gingivalis)." (PMID 39253090, 2024). "Cytokines such as interleukins (IL)-1β, IL-2, IL-6, and tumor necrosis factor (TNF)-α, along with their receptors, are implicated in tissue destruction and bone loss in both conditions, and are reported to connect periodontitis and other immune-mediated inflammatory diseases." (PMID 38790898, 2024). "Multiple polymorphisms have been identified in the promoter region of TNF-α, and the 308G/A and 863C/A polymorphisms may contribute to susceptibility to periodontitis according to a meta-analysis." (PMID 38920850, 2024). "Additionally, inflammatory markers such as IL-1b, IL-6 and TNF-α are associated with periodontitis and HIV, and possibly elicit HIV reactivation." (PMID 38885222, 2024). "Our findings that periodontitis and MetS cause a significant increase in thr serum TNF-α level and IL-1β/IL-10 ratio and that the combined presence of these diseases exacerbates systemic inflammatory stress are compatible with the consensus in previous studies." (PMID 39590401, 2024). "TNF-α and IL-1β levels were shown to have an association with periodontitis." (PMID 39410587, 2024). "Emerging evidence indicates that MAIT cells may contribute to the development of periodontitis by producing proinflammatory cytokines like IL-17 and TNF when activated by pathogenic microorganisms in the oral cavity." (PMID 38919613, 2024). "Higher systemic circulating inflammatory burden of CVD risks such as interleukin (IL)-1β, IL-8, IL-6 and tumor necrosis factor-alpha (TNF-α) are directly associated with the periodontitis incipient lesions in adolescents and established periodontitis in adults." (PMID 37711554, 2023). "Similarly, in samples of individuals with chronic and aggressive periodontitis, Kurtis et al17 found a strong association between salivary TNF-α levels and periodontal clinical indices (PPD, CAL, PI, and GI)." (PMID 36794778, 2023). "Antihypertensive blockers of Ang II receptors have been effective in inhibiting the production of IL-6, TNF-α, and receptor activator of the nuclear factor kappa-Β ligand, and consequently, they reduce alveolar bone loss in rats with experimental periodontitis." (PMID 37568542, 2023). "In experimental periodontitis, TNF-α antagonists reduced bone loss by 50%." (PMID 36896188, 2023). "In a previous study of a periodontitis model, there was increased gingival expression of inflammatory mediators, including molecules that are implicated in bone resorption such as interleukin (IL)-6, TNF, and IFN-γ." (PMID 38029238, 2023).
periodontitis (continued). "In addition, the IL‐1β/IL‐10 ratio and TNF‐α/IL‐4 ratio in the biopsies of periodontitis patients are strongly associated with the severity of periodontitis." (PMID 37647428, 2023). "Additionally, new research has linked elevated blood TNF levels to the severity of disease progression in individuals with periodontitis who are experiencing active attachment loss." (PMID 37377463, 2023). "This peptide at a concentration of 320 μg/mL induces cell death in P. gingivalis Furthermore, in P. gingivalis-induced periodontitis in a rat model, a decrease of IL-1β and TNF-α production and inhibition of bone loss was observed after incubating P. gingivalis with this peptide." (PMID 36897441, 2023). "TNF-α, a cytokine secreted by macrophages, has activity like IL-1B and is linked to the tissue destruction process caused by periodontal disease and its presence in saliva is more associated with patients with periodontitis than healthy patients (P =0.0004)." (PMID 37026605, 2023). "The reduction in Bmal1 levels may trigger further production of TNF-α and other proinflammatory factors and exacerbate periodontal inflammation and bone loss in gingivitis and periodontitis." (PMID 36467684, 2022). "Inflammatory factors such as tumor necrosis factor-α (TNF-α), interleukin-1β interleukin (IL)-1β, IL-6, and IL-17 play an important role in the pathology of chronic periodontitis because they cause secondary damage to periodontal tissues thereby exacerbating the destruction of periodontal tissues." (PMID 35942384, 2022). "Both TNFα and IL-1 play bone destructive roles which contribute to bone loss in periodontitis." (PMID 35293424, 2022). "Furthermore, an in vivo study reported that orthodontic force up-regulated the expression of IL-1β and TNF-α in periodontitis rats and amplified bone loss." (PMID 34185172, 2022). "Endothelial dysfunction and injury caused by pro-inflammatory mediators of chronic periodontitis such as tumor necrosis factor-α (TNF-α), interleukin (IL)-1, and IL-6 could also affect the vasculogenic pathway resulting in erectile dysfunction." (PMID 35757444, 2022). "It is possible that downregulation of macrophage-specific Act1 could aggravate periodontitis and accelerate alveolar bone loss via TNF/NF-κB signaling." (PMID 36297683, 2022). "Periodontitis is the main cause of tooth loss, and it closely related to the increase of the pro-inflammatory factors interleukin-1 (IL-1), tumor necrosis factor-α (TNF-α) and IL-68." (PMID 35538156, 2022). "Other meta-analysis, however, supported that variant A of the TNF-α (G −308A) polymorphism may contribute to chronic periodontitis and aggressive periodontitis susceptibility, particularly in Asians and Caucasians." (PMID 35454140, 2022). "Periodontitis-associated bacteria promote the production of pro-inflammatory mediators, such as interleukin, TNF-α, and matrix metalloproteinase, which are released into the oral microenvironment, causing chronic inflammation, and promoting tumor cell migration and invasion." (PMID 36046741, 2022). "Collectively, TNF-α-preconditioned GMSC-derived exosomes may be a promising therapeutic tool against periodontitis and other inflammatory disorder leading to bone loss." (PMID 33359765, 2021). "In two case-control studies, TNF-α G-308A polymorphism was associated with increased risk of peri-implantitis in dominant model (AA+GA vs GG), which was still significant after adjustment for smoking and positive history of periodontitis." (PMID 34610045, 2021). "Our study also demonstrates that the altered oral microbiota in diseased sites affected the cytokines levels, demonstrating a significant positive correlation between pro-inflammatory TNF-α and taxa known to be associated with pathogenesis of periodontitis, such as Actinomyces, and Fusobacterium." (PMID 34835489, 2021).